DACT2 (dishevelled binding antagonist of beta catenin 2)
Description:
Involved in regulation of intracellular signaling pathways during development. Negatively regulates the Nodal signaling pathway, possibly by promoting the lysosomal degradation of Nodal receptors, such as TGFBR1. May be involved in control of the morphogenetic behavior of kidney ureteric bud cells by keeping cells epithelial and restraining their mesenchymal character. May play an inhibitory role in the re-epithelialization of skin wounds by attenuating TGF-beta signaling (By similarity).
Synonyms: C6orf116; bA503C24.7; DAPPER2; DPR2
Tractability: No criterion of Open Targets' tractability assessment is met for any kind of drug.
Gene: Protein-coding gene on chromosome 6 (168,292,830 to 168,319,777, reverse strand). Ensembl gene ENSG00000164488.
Gene Ontology:
Molecular function: beta-catenin binding; delta-catenin binding; protein kinase A binding; protein kinase C binding; transcription factor binding
Biological process: epithelial cell morphogenesis; inner medullary collecting duct development; negative regulation of cell adhesion; negative regulation of nodal signaling pathway; skin development
Cellular component: cytoplasm
Genetic constraint (gnomAD): Loss-of-function variants: 13 observed, 14.03 expected, observed/expected ratio (o/e) 0.93, 90% interval 0.6 to 1.47. The upper end of that interval is the gene's LOEUF score, 1.47, which puts it in group 6 of 6, group 1 being the genes least tolerant of losing a copy. Missense variants: 920 observed, 911.72 expected, observed/expected ratio (o/e) 1.01, 90% interval 0.95 to 1.07. Synonymous variants: 400 observed, 408 expected, observed/expected ratio (o/e) 0.98, 90% interval 0.9 to 1.07.
Homologues: Orthologues: chimpanzee DACT2 (98% identical), macaque DACT2 (93% identical), rat Dact2 (58% identical), dog DACT2 (56% identical), mouse Dact2 (55% identical), pig DACT2 (50% identical), guinea pig Dact2 (47% identical), zebrafish dact2 (30% identical). Paralogues in human: DACT1 (24% identical), DACT3 (17% identical).
Diseases named in the same sentence as DACT2 in open-access papers:
DACT2 is named in the same sentence as 34 diseases in open-access papers, as found by Europe PMC text mining. Sharing a sentence is not in itself a finding about the gene and the disease. The quoted sentences say what the papers report.
breast carcinoma (8 papers, 2016 to 2022). "Reduced DACT2 expression was significantly associated with promoter region methylation in primary breast cancer (P < 0.05)." (PMID 28607412, 2017). "Here, we further examined DACT2 as a negative regulator of Wnt signaling and found that its transcription is repressed in breast cancer cell lines and primary tumors, which is associated with its promoter CpG methylation." (PMID 27708215, 2016). "Reduction of miR-503-3p repressed glycolysis and promoted mitochondrial oxidative phosphorylation in breast cancer cells and decreased tumor growth by overexpressing DACT2 and inactivating the Wnt/β-catenin signaling pathway." (PMID 35864965, 2022). "The result indicated that the DSVs in SNTG2, PCMT1, DACT2, CBX3, ATP11A, and SHC2 were associated with breast cancer." (PMID 33431054, 2021). "We demonstrated that DACT2 suppresses human breast cancer growth by inhibiting the Wnt/β-catenin signaling pathway." (PMID 28607412, 2017). "In conclusion, our data indicate that DACT2 is frequency methylated in human breast cancer and the expression of DACT2 is regulated by promoter region methylation." (PMID 28607412, 2017). "Methylation of DACT2 was examined in 153 cases of human primary breast cancer and 5 cases of normal breast tissue samples." (PMID 28607412, 2017). "In this study, we found that DACT2 is frequently methylated in human breast cancer, and the expression of DACT2 is regulated by promoter region methylation." (PMID 28607412, 2017). "DACT2 inhibited Wnt/β-catenin signaling in human breast cancer cells and suppressed breast cancer cell tumor growth in xenograft mice." (PMID 28607412, 2017). "The expression of DACT2 was analyzed by immunohistochemistry in 33 cases of available matched breast cancer and adjacent tissue samples." (PMID 28607412, 2017). "The effects of DACT2 on Wnt/β-catenin signaling were analyzed by DACT2 overexpression and siRNA knockdown techniques in human breast cancer cells." (PMID 28607412, 2017). "In conclusion, our results demonstrate that DACT2 is frequently methylated in human breast cancer, methylation of DACT2 activates Wnt signaling, and DACT2 suppresses breast cancer cell growth both in vitro and in vivo." (PMID 28607412, 2017). "We showed the tumor-specific methylation of DACT2 in breast cancer, which suggests its potential as a tumor marker." (PMID 27708215, 2016). "The results indicated that promoter methylation is a major mechanism of DACT2 silencing in breast cancer cells." (PMID 27708215, 2016). "Demethylation of BT549 and T47D cell lines with 5-aza-2'-deoxycytidine restored DACT2 expression along with promoter demethylation, suggesting that its downregulation in breast cancer is dependent on promoter methylation." (PMID 27708215, 2016). "DACT2 inhibited breast cancer cell proliferation by inducing apoptosis, and further suppressed tumor cell migration." (PMID 27708215, 2016). "DACT2 methylation was detected in 73% (107/147) of breast cancer tissues, 20% (1/5) of breast tumor adjacent tissues and none of normal breast tissues, suggesting the tumor-specific methylation of DACT2 in breast cancer." (PMID 27708215, 2016). "The biological functions of DACT2 in breast cancer cells were assessed in vitro in the context of Wnt/β-catenin signaling." (PMID 27708215, 2016). "We investigated DACT2 expression in breast cancer cell lines and primary tumors, as well as its functions and molecular mechanisms." (PMID 27708215, 2016). "DACT2 expression in human breast cancer samples was analyzed using the online database Oncomine and qRT-PCR." (PMID 27708215, 2016). "In summary, DACT2 was found to be an antagonist to Wnt/β-catenin signaling and was frequently downregulated/silenced in breast cancer." (PMID 27708215, 2016).
breast carcinoma (continued). "We next analyzed the correlation between DACT2 methylation and clinicopathological features of breast cancer patients, including age, tumor size, tumor grade, lymph node metastasis, and estrogen receptor (ER), progesterone receptor (PR) and HER2 status." (PMID 27708215, 2016). "In addition, decreased expression and promoter hypermethylation of DACT1 and DACT2 have been found in some primary tumors and tumor cell lines, including hepatocellular carcinoma, breast cancer, lung cancer, colorectal cancer and some other cancers." (PMID 28077137, 2017). "DACT2 was methylated in 49.7% (76/153) of primary breast cancer samples." (PMID 28607412, 2017). "In this study, we also found that DACT2 suppresses breast cancer cell migration and invasion." (PMID 28607412, 2017). "DACT2 suppresses breast cancer development by inhibiting canonical Wnt signaling." (PMID 28607412, 2017). "In this study, we explored the epigenetic regulation and function of DACT2 in human breast cancer." (PMID 28607412, 2017). "Re-expression of DACT2 suppresses breast cancer cell growth in vitro and in vivo." (PMID 28607412, 2017). "DACT2 suppressed breast cancer cell growth and induced G1/S phase arrest in breast cancer cells." (PMID 28607412, 2017). "We previously identified DACT2 as a methylated target in our breast cancer methylome study." (PMID 27708215, 2016). "Furthermore, overexpression of DACT2 in MB231 breast cancer cell lines resulted in a profound reduction of both total and phosphorylated forms of Akt and GSK-3β." (PMID 27708215, 2016). "Furthermore, DACT2-transfected cells had lower invasion rates than control cells, suggesting that DACT2 attenuates wound-induced cell migration and inhibits the invasiveness of breast cancer cells." (PMID 27708215, 2016). "Our results indicate that DACT2 acts as an important TSG for breast cancer, which may serve as a potential biomarker or therapeutic stargeting strategy for breast cancer." (PMID 27708215, 2016). "We next performed RT-PCR analysis to examine DACT2 expression in nine breast cancer cell lines." (PMID 27708215, 2016). "The mechanism of DACT2 in human breast cancer remains unclear." (PMID 28607412, 2017). "Therefore, DACT2 methylation is a potential breast cancer detection marker." (PMID 28607412, 2017). "Moreover, the data from breast cancer research indicated that expression of p-AKT and p-GSK-3β dramatically decreased in breast cancer cells upon DACT2 re-expression, which indicated DACT2 might regulate Akt/GSK-3 signaling pathway to involve in migration and invasion." (PMID 35864965, 2022). "Moreover, multivariate diagnostic analysis of the methylation status of WIF1, Sostdc1, and DACT2 showed up to 91% specificity and 100% sensitivity in discriminating breast cancer (invasive and non-invasive) from benign tumours and controls and may be a complementary tool for breast cancer diagnosis." (PMID 36338475, 2022). "DACT2 was methylated in 49.7% (76/153) of human primary breast cancer, and no methylation was found in normal breast tissue samples." (PMID 28607412, 2017). "Here, we showed that DACT2 is expressed in normal breast tissues but frequently downregulated/silenced by promoter methylation in breast cancer cell lines and primary tumors, but not in normal breast tissues." (PMID 27708215, 2016). "The average level of DACT2 mRNA expression in breast cancer tissues was 2.25-fold lower than that in adjacent non-cancerous tissues (p<0.05)." (PMID 27708215, 2016). "Hence, combination of SOSTDC1, DACT2 and WIF1 was effective in differentiating breast cancer [non-invasive and invasive] from benign diseases of the breast and healthy individuals and could help as a complementary diagnostic tool for breast cancer." (PMID 34997107, 2022).
hepatocellular carcinoma (6 papers, 2013 to 2024). A malignant tumor that arises from hepatocytes. "Zhang et al34 uncovered that reduction of DACT2 expression was associated with promoter hypermethylation and restoration of DACT2 expression could be induced by 5‐Aza in human hepatocellular carcinoma." (PMID 30039914, 2018). "Our previous studies found that DACT2 is a Wnt/β-catenin signaling inhibitor in lung and hepatocellular carcinoma." (PMID 25375359, 2014). "In the current study, we found that the expression level of DACT2 was downregulated in human hepatocellular carcinoma by quantitative RT-PCR and immunohistochemical analysis." (PMID 23496880, 2013). "DACT2 was found frequently methylated in human lung cancer and hepatocellular carcinoma." (PMID 25375359, 2014). "Significant down-regulation of DACT2 expression was also observed in NSCLC tissues, colorectal cancer and hepatocellular carcinoma (HCC) tissues compared to normal tissues 44-48." (PMID 35864965, 2022).
colon cancer (5 papers, 2013 to 2024). "Investigation of the mechanism of G2/M cell cycle arrest was based on a previous report that DACT2 suppressed β-catenin activity in colon cancer by competition for LEF1 binding." (PMID 30359298, 2018). "Similar to the previous report on colon cancer cells, we found that DACT2 expression was present at very low or undetectable levels in some HCC cell lines and that 5-Aza-dC restored the transcription level of DACT2." (PMID 23496880, 2013). "Similar to DACT1, ectopic expression of DACT2 led to a significant increase of apoptotic cells 15, 16, 91, induction on the expression of Bax in glioma cells 16, and the enhanced cleavage of PARP in colon cancer cells." (PMID 35864965, 2022).
colorectal cancer (4 papers, 2013 to 2024). A primary or metastatic malignant neoplasm that affects the colon or rectum. "Because of the possible role of DACT2 in tumor suppression and its reduced expression in cancer, the correlation of DACT2 expression and its methylation status have been characterized in colorectal cancer." (PMID 23496880, 2013). "Moreover, in colorectal cancer cell lines, kaempferol can bind DNMT1 and downregulate the methylation of tumor suppressor gene DACT2, thus inhibiting the Wnt/β-catenin pathway." (PMID 39858410, 2024).
esophageal cancer (4 papers, 2016 to 2022). A primary or metastatic malignant neoplasm involving the esophagus. "The association of DACT2 methylation with tumor stage suggests that methylation of DACT2 is related to esophageal cancer progression." (PMID 26919254, 2016). "Loss of expression or reduced expression of DACT2 correlated with promoter region hypermethylation in esophageal cancer cells." (PMID 26919254, 2016). "DACT2 suppressed colony formation, cell migration and invasion in esophageal cancer cells, and it also suppressed esophageal cancer cell xenograft growth." (PMID 26919254, 2016). "In conclusion, DACT2 is frequently methylated in human esophageal cancer and its expression is regulated by promoter region methylation." (PMID 26919254, 2016). "Our further investigation found that DACT2 suppresses esophageal cancer growth both in vitro and in vivo, indicating that it acts as a tumor suppressor in human esophageal cancer." (PMID 26919254, 2016). "We conclude from these combined results that DACT2 suppresses esophageal cancer growth by inhibiting both Wnt signaling and TGF-β inhibiting." (PMID 26919254, 2016). "The mechanisms of DACT2 in esophageal cancer were analyzed in this study." (PMID 26919254, 2016). "The epigenetic changes and functions of DACT2 in human esophageal cancer remain to be elucidated." (PMID 26919254, 2016). "The methylation status and function of DACT2 remain to be elucidated in human esophageal cancer." (PMID 26919254, 2016). "The expression of DACT2 was detected by semi-quantitative RT-PCR in human esophageal cancer cells." (PMID 26919254, 2016). "DACT2 suppresses esophageal cancer growth by inhibiting Wnt signaling." (PMID 26919254, 2016). "In conclusion, DACT2 is frequently methylated in human esophageal cancer." (PMID 26919254, 2016). "DACT2 inhibited Wnt signaling in human esophageal cancer cells." (PMID 26919254, 2016). "However, it remains to be elucidated which signaling pathway is primarily involved in the initiation of esophageal carcinogenesis and which signaling pathway is responsible for esophageal cancer progression and metastasis driven by DACT2." (PMID 26919254, 2016). "DACT2 suppresses esophageal cancer development by inhibiting the Wnt signaling pathway." (PMID 26919254, 2016). "In the present study, we found the expression of DACT1, DACT2 and DACT3 were frequently silenced or decreased in esophageal cancer cell lines." (PMID 28077137, 2017). "Frequent reduced expression of DACT1, DACT2 and DACT3 were found in esophageal cancer cell lines and the expression levels of DACT1 and DACT2 were reversed by 5-Aza-Dc." (PMID 28077137, 2017). "DACT2 is frequently methylated in human esophageal cancer; methylated DATC2 accelerates esophageal cancer development by activating Wnt signaling." (PMID 27818681, 2016). "In addition, the inhibition of proliferation and migration was further detected in TE1 and TE13 cells after treatment with 5-Aza-Dc or stable transfection of DACT1 or DACT2 plasmid, indicating the tumor suppressor role of DACT1 and DACT2 in esophageal cancer cell lines." (PMID 28077137, 2017).
gastric cancer (4 papers, 2016 to 2025). A primary or metastatic malignant neoplasm involving the stomach. "Our previous studies demonstrated that DACT2 suppresses tumor proliferation by inhibiting canonical Wnt signaling in human hepatic, lung, thyroid and gastric cancers." (PMID 26919254, 2016). "Moreover, the decreased expression of DACT2 is closely correlated with the invasion, metastasis, occurrence, and development of gastric cancer, prostate, and papillary thyroid cancer 52-55." (PMID 35864965, 2022). "Previous studies have demonstrated that miR-214-3p can regulate the proliferation, apoptosis, and metastasis of gastric cancer cell lines (e.g., SGC-7901, BGC-823, and GC9811) through distinct target genes, including A2AR, PRDM16, PTEN, and Dact2." (PMID 41318488, 2025).
glioma (4 papers, 2017 to 2022). A benign or malignant brain and spinal cord tumor that arises from glial cells (astrocytes, oligodendrocytes, ependymal cells). "In the present study, we explored the biological impact of DACT2 on the progression of glioma and explored the mechanisms underlying its tumor suppressor role." (PMID 28796248, 2017). "In this study, we investigated the role of DACT2, underlying molecular mechanisms and its clinical significance in glioma patients." (PMID 28796248, 2017). "In addition, IHC assay revealed that DACT2 overexpression upregulated the expression of Bax and downexpressed the expression of YAP, PCNA and CyclinD1 and in glioma tissues, and DACT2 knockdown caused opposide result." (PMID 28796248, 2017). "Our previous study proved that proliferation was inhibited, and G1/S arrest was enhanced by overexpression of DACT2 in glioma cells." (PMID 35864965, 2022). "Expression levels of DACT2 in glioma tissues significantly correlated with the WHO grade, Karnofsky Performance Score and age16." (PMID 35864965, 2022). "To further examine the biological effect of DACT2 on glioma cell, we overexpressed DACT2 in the glioma cell lines." (PMID 28796248, 2017). "Overexpression of DACT2 in glioma cells inhibited proliferation, cell cycle and enhanced apoptosis, sensitivity to temozolomide in vitro and suppressed tumor growth in vivo." (PMID 28796248, 2017). "qRT-PCR and Western Bolt revealed that DACT2 was significantly downexpressed in glioma tissues compared with the paired adjacent tissues at mRNA and protein levels." (PMID 28796248, 2017). "Two glioma cells (U251 and U87) that showed low expression of DACT2 were selected for overexpressing experiments via a lentivirus-based method and SHG44 and A172, which showed high expression of DACT2 were used for knockdown experiments." (PMID 28796248, 2017). "In the current study, we found that DACT2 was frequently downexpressed in the glioma tissues in comparison to normal brain tissues by qRT-PCR, western blot and immunohistochemical analysis." (PMID 28796248, 2017). "The Kaplan–Meier curve revealed that patients with lower DACT2 expression had a significantly poorer overall survival (OS) compared to patients with higher DACT2 expression in gliomas with different grades." (PMID 28796248, 2017). "qRT-PCR and western blot analysis were used to evaluate the expression levels of DACT2 in four glioma cell lines (U87, U251, SHG44 and A172)." (PMID 28796248, 2017). "Next, we assessed the mRNA and protein expression of DACT2 in eight glioma tissues and paired adjacent tissues." (PMID 28796248, 2017). "In conclusion, we showed for the first time that DACT2 was downexpressed in gliomas and decreased DACT2 was correlated with glioma grade and poor survival." (PMID 28796248, 2017). "The results showed that overexpression of DACT2 significantly increased the population of G0/G1 phase cells in DACT2 overexpressing glioma cells, and decreased S phase cells compared with control cells." (PMID 28796248, 2017). "Flow cytometry analysis revealed that overexpression of DACT2 in both glioma cells markedly induced apoptosis compared with control cells and increased tunel positive cells." (PMID 28796248, 2017). "Downexpression of DACT2 in gliomas compared with adjacent normal brain tissues was correlated with glioma grade and poor survival." (PMID 28796248, 2017). "Reduced DACT2 expression markedly affected the outcome of patients with glioma, and was correlated with poor survival." (PMID 28796248, 2017). "In addition, The Cancer Genome Atlas (TCGA) glioma data set also showed lower expression of DACT2 in higher grade glioma." (PMID 28796248, 2017). "Our findings suggest that DACT2 is a novel tumor suppressor gene and may be a potential therapeutic target in gliomas." (PMID 28796248, 2017). "Whereas knockdown of DACT2 reduced the rate of apoptosis in glioma cell." (PMID 28796248, 2017).